ALB (albumin)
Diseases named in the same sentence as ALB in open-access papers (continued):
Sharing a sentence is not in itself a finding about the gene and the disease.
type 2 diabetes (continued). "The lower serum albumin levels can be partially attributed to the increased urinary albumin excretion due to hyperglycemia in type 2 diabetes patients." (PMID 39125606, 2024). "We aimed to explore the associations between urine albumin-to-creatinine ratio (uACR) and cardia-cerebrovascular disease (CVD) in Chinese population with type 2 diabetes(T2D)." (PMID 38291519, 2024). "This cross-sectional study identified a significant inverse relationship between serum albumin levels and diabetic retinopathy in patients with type 2 diabetes." (PMID 38369636, 2024). "Findings from a randomized clinical trial supported the idea that vitamin C and E supplementation can protect renal function by reducing urinary albumin and improving glomerular function in individuals with type 2 diabetes." (PMID 38186336, 2024). "In type 2 diabetes patients with different urine albumin-to-creatinine ratios (UACR), serum HIF-1α concentrations were significantly elevated, along with significantly increased concentrations of serum BUN and serum creatinine." (PMID 39748872, 2024). "Albuminuria testing, specifically the measurement of urinary albumin-to-creatinine ratio (uACR), has been recommended to assess renal function in patients with type 2 diabetes(T2D)." (PMID 38291519, 2024). "The screening for CKD, through regular measurement of the albumin-to-creatinine ratio and glomerular filtration rate, is widely recommended for individuals with type 2 diabetes as part of the annual cycle of care starting from the time of diagnosis." (PMID 38694939, 2024). "A study has demonstrated that vitamin C and E supplementation, as well as a combination of magnesium, zinc, and vitamins C and E, can decrease urinary albumin excretion levels and improve glomerular function in type 2 diabetes patients." (PMID 39145317, 2024). "A clinical trial demonstrated that zinc supplementation reduces urinary albumin excretion in type 2 diabetes patients with microalbuminuria." (PMID 38674257, 2024). "As important components in the blood, fibrinogen and albumin corresponds closely to type 2 diabetes." (PMID 37576498, 2023). "The recruited patients had type 2 diabetes, a normal urinary albumin excretion, and preserved kidney function." (PMID 37298105, 2023). "Emerging studies have found that exenatide can decrease urinary albumin excretion in patients with type 2 diabetes." (PMID 37090383, 2023). "Adding esaxerenone to the existing renin-angiotensin system inhibitor therapy in patients with type 2 diabetes and microalbuminuria has shown to increase the likelihood of the normalization of the albumin levels and reduced progression of albuminuria." (PMID 36704237, 2023). "Although albuminuria has been linked to heart failure in the general population, the relationship between urine albumin-to-creatinine ratio (uACR) and heart failure in type 2 diabetes patients is not well understood." (PMID 36966320, 2023). "Higher cerebrospinal fluid pressure, higher white blood cell counts, higher neutrophil percentage, deep coma and lower albumin were independent factors for poor outcomes of adult JE." (PMID 38179427, 2023). "Our study found a significant association between diabetic peripheral neuropathy diagnosed using DPN-Check® and urinary albumin excretion in patients with type 2 diabetes, particularly in female patients." (PMID 37373782, 2023). "Type 2 diabetes patients had significantly lower serum albumin levels than normal people, and the decrease in albumin level was also closely related to cognitive impairment and dementia (Kunutsor, Khan & Laukkanen, 2015)." (PMID 37576498, 2023). "The urine albumin–creatinine ratio (uACR) is a warning for the deterioration of renal function in type 2 diabetes (T2D)." (PMID 35806944, 2022).
type 2 diabetes (continued). "Hyperfibrinogenaemia is common in type 2 diabetes, and synthesis of fibrinogen is up-regulated in type 2 diabetic patients with increased urinary albumin excretion, which implies that high FIB concentration is consistent with albuminuria." (PMID 35802685, 2022). "One of the oxidative effects generated by free radicals is a change in albumin protein structure in type 2 diabetic patients." (PMID 35563162, 2022). "Furthermore, serum albumin has already been inversely associated with adipose tissue inflammation, adiposity, and glucose regulation, and could even predict the risk of developing type 2 diabetes in a longitudinal cohort of healthy adults." (PMID 36235652, 2022). "Subjects with low vitamin D levels (<20 mmg/dl) were more likely to be female, have type 2 diabetes, higher HbA1c, D-dimer and ferritin levels and lower oxygen saturation, albumin and C-reactive protein." (PMID 35155539, 2022). "In our study, the higher albumin level was the protective factor, and CCI score ≥3 was the risk factor for all-cause death in patients with pulmonary TB and type 2 diabetes comorbidity." (PMID 34513785, 2021). "Serum apelin is higher in diabetes type 2 patients as compared to healthy individuals and it is positively correlated to urinary albumin excretion." (PMID 34206927, 2021). "Among patients with acetaminophen-associated ALF, those with prior BS had higher INR, lower serum albumin, and a trend toward a higher coma grade." (PMID 33090351, 2021). "The frequency of regular urinary albumin:creatinine determinations was comparable in type 1 (44.1 %) and type 2 diabetes (49.1 %)." (PMID 34011313, 2021). "The proportion of patients who received at least one eGFR and one albumin:creatinine determination was comparable in type 1 (44.1 %) and type 2 diabetes (49.1 %)." (PMID 34011313, 2021). "PCOS is associated with cardiometabolic risk factors such as obesity, insulin resistance (IR)/type 2 diabetes mellitus (T2DM), hyperleptinemia, increased blood pressure (BP), and increased urinary albumin to creatinine ratio." (PMID 33806551, 2021). "In conclusion, the lower albumin level, older age, and CCI score ≥3 were predictors of all-cause death in patients with pulmonary TB and type 2 diabetes comorbidity." (PMID 34513785, 2021). "This analysis confirmed the trend observed in the discovery proteomics approach and supports trioxidation of human serum albumin as a strong candidate biomarker for type 2 Diabetes." (PMID 33807006, 2021). "It recommends SGLT-2i use in those patients with type 2 diabetes with an eGFR ≥ 30 mL/min/1.73 m2 and urinary albumin > 30 mg/g creatinine, particularly in those with urinary albumin > 300 mg/g creatinine." (PMID 34011313, 2021). "Main findings:When type 2 diabetes was detected by glycated plasma proteins (albumin or fructosamine; n = 24), average HbA1c was mean (SD) 5.2% (0.4).OGTT detected prediabetes in 74 individuals (13 of 74 had low HbA1c)." (PMID 33705304, 2021). "The RGD peptide agent is proven to significantly reduce kidney impairment symptoms, such as albumin excretion and mesangial expansion, in people with type 2 diabetes and mice with Ins2Akita/+type 1 diabetes." (PMID 34630950, 2021). "A recent study identified human serum albumin as a putative biomarker for diagnosing and monitoring type 2 diabetes progression." (PMID 33807006, 2021). "This study aimed to evaluate the associations of the non-albumin protein (NAP) with different urinary marker for tubular and glomerular damage in patients with type 2 diabetes (T2D)." (PMID 32631266, 2020). "BMI, blood pressure, HbA1c levels, LDL-cholesterol, triglycerides, and urinary albumin-to-creatinine ratio in patients with type 2 diabetes were higher, and HDL-cholesterol was lower than those in control subjects." (PMID 32184758, 2020).
type 2 diabetes (continued). "Inclusion criteria were diagnosis of type 2 diabetes, age 30‐75 years, dipstick proteinuria of ≥1+ or urinary albumin‐to‐creatinine ratio (UACR) of ≥30 mg/g and estimated glomerular filtration rate of ≥30 mL/min/1.73 m2." (PMID 32704573, 2020). "The spectral Raman analysis of albumin was performed using artificial urine, at five concentrations of albumin and 24 h collection urine samples from ten patients with Type 2 Diabetes." (PMID 32138353, 2020). "Urinary albumin excretion remains the key biomarker to detect renal complications in type 2 diabetes." (PMID 32138353, 2020). "In the samples from patients with type 2 diabetes, we identified the presence of albumin in the peaks of the spectrum located at 663.07, 993.43, 1021.43, 1235.28, 1429.91 and 1633.91 cm−1." (PMID 32138353, 2020). "In this pilot study, we evaluated the performance of Raman spectroscopy in the assessment of urinary albumin in patients with type 2 diabetes." (PMID 32138353, 2020). "The capability of Raman spectroscopy for detection of small concentrations of urinary albumin suggests the feasibility of this method for the screening of type 2 diabetes renal complications." (PMID 32138353, 2020). "Renal dysfunction, a major complication of type 2 diabetes, can be predicted from estimated glomerular filtration rate (eGFR) and protein markers such as albumin concentration." (PMID 32545899, 2020). "After dual CCR2 and CCR5 receptor antagonist treatments, the urinary albumin-to-creatinine ratio was reduced in type 2 diabetes patients who also received standard of care, such as ACEi or ARB." (PMID 32365893, 2020). "We enrolled 287 patients with type 2 diabetes, who were classified into normoalbuminuria (n = 144), microalbuminuria (n = 94), or macroalbuminuria (n = 49) groups based on their urine albumin to creatinine ratios (UACR), along with 42 healthy controls." (PMID 31218128, 2019). "GK rats have mild phenotypes for DN among type 2 diabetic rodent models, but they exhibit increased plasma UN and creatinine levels at the age of 10 weeks and increased urinary albumin excretion at the age of 2 months." (PMID 31467929, 2019). "Treatment with CCX140-B in patients with type 2 diabetes and nephropathy resulted in a reduced albumin–creatinine ratio." (PMID 29910771, 2018). "Kondaveeti SB, Shaker A, Chidambaram R. Utility of glycated albumin in diagnosis of type 2 diabetes: an Indian perspective study." (PMID 29527102, 2018). "It is also in line with the neutral results of the recently published MARLINA-T2D trial, which did not confirm previous suggestions of an improvement in acute glomerular damage measured by the urinary albumin-creatinine ratio in subjects with type 2 diabetes." (PMID 29773079, 2018). "The use of NOX-E36 (empaticap pegol) which binds and inhibits MCP-1 resulted in a reduction of albumin–creatinine ratio in patients with type 2 diabetes." (PMID 29910771, 2018). "Neutrophils are positively correlated with urinary albumin excretion in patients with type 2 diabetes while lymphocytes are negatively correlated." (PMID 29910771, 2018). "The results in the present study provided evidences that the Chinese herbal medicine SYFSF significantly decreased the urinary albumin, serum cholesterol, and triglyceride levels, as well as alleviated the renal lesions in a rat model with type 2 diabetes." (PMID 28713834, 2017). "Serum albumin concentration continuously increased in subjects with prediabetes who returned to normal glycemic status, compared to those who developed overt type 2 diabetes." (PMID 28430803, 2017). "Further studies remain highly warranted in order to reach a better understanding of the potential interest of glycated albumin, oxidative stress, and glycoxidation parameters in the monitoring of type 2 diabetic patients." (PMID 29362717, 2017).
type 2 diabetes (continued). "For example, Met-111 and Met-147 of serum albumin showed far lower baseline [Met(O)]/[Met] than Met-1181 of complement C3, but these residues were clearly more oxidized in patients with type 2 diabetes and renal failure." (PMID 27929071, 2016). "This was supported by a randomized controlled trial showing that individuals with type 2 diabetes and microalbuminuria had a greater increase in blood pressure and increase in albumin excretion ratio during high sodium intake (250 mmol/24 h for 7 days)." (PMID 28066329, 2016). "We randomly assigned 237 type 2 diabetic patients with high-normal albuminuria (10 to <30 mg/g of albumin-to-creatinine ratio) or microalbuminuria (30 to <300 mg/g) to the DRI group or ARB group (any ARB) with a target blood pressure of <130/80 mmHg." (PMID 28033332, 2016). "This historical cohort study included patients with type 2 diabetes, spot urine albumin:creatinine ratio (ACR) <300 mg/gCr and normal serum creatinine concentrations treated between August 1988 and April 2015." (PMID 27210499, 2016). "A recent study showed that normotensive subjects with type 2 diabetes and microalbuminuria had higher morning blood pressure than either of the normotensive subjects with type 2 diabetes and normal urinary albumin excretion or age-matched controls." (PMID 26824045, 2016). "This study aimed to determine the activities of N-acetyl-β-D-glucosaminidase and alanine aminopeptidase and albumin concentration in urine samples of patients with type 2 diabetes." (PMID 27594733, 2016). "Because glycation of plasma proteins occurs more readily than glycation of hemoglobin, glycated albumin should serve well in the evaluation of glycemic control for both type 1 and type 2 diabetes." (PMID 26765575, 2016). "Strikingly, glycated β-lipoprotein was markedly increased in type 2 diabetes patients with microvascular complications and the rise was disproportionate to that in glycated albumin." (PMID 27896233, 2016). "The MARLINA-T2DM (efficacy, safety, and modification of albuminuria in type 2 diabetes subjects with renal disease with linagliptin) trial is ongoing, in order to evaluate the albumin-lowering potential of linagliptin in T2DM patients with renal impairment." (PMID 26075286, 2015). "This was shown in a prior study of mouse models of type 2 diabetes with nephropathy in which 8 weeks of consuming a ketogenic diet fully normalized albumin : creatinine ratios and the expression of stress-related genes." (PMID 26185688, 2015). "Patients with ESRD resulting from type 2 diabetes requiring dialysis who had ≥20 % glycated albumin (GA) were enrolled." (PMID 26550558, 2015). "In a cross-sectional study, Tseng verified an independent correlation between serum uric acid (UA) and urine albumin excretion in Taiwanese type 2 diabetic patients." (PMID 24772444, 2014). "In our previous study, QHYH was demonstrated to reduce urinary albumin excretion (UAER) in type 2 diabetes patients." (PMID 24505445, 2014). "A clinical study in Japan showed that the N-hydroxyethyl derivative of 1-DNJ (miglitol) decreased the urinary albumin excretion rate in Japanese patients with type 2 diabetes." (PMID 24744808, 2014). "In the present study, plasma α-klotho levels in patients with type 2 diabetes were highest in the normoalbuminuria stage and decreased with increasing urinary albumin excretion." (PMID 25084095, 2014). "In a Korean study on type 2 diabetes patients, baPWV was significantly correlated with mean blood pressure, heart rate, age, urine albumin/creatinine ratio." (PMID 25126115, 2014). "Elevated urine albumin excretion ratio (UAER) is a key risk factor for renal and cardiovascular disease in type 2 diabetes." (PMID 24864150, 2014). "A cross-sectional study was performed in 475 community-based patients with type 2 diabetes (190 males and 285 females) with normal urinary albumin-to-creatinine ratios (UACR) (< 3.5 mg/mmol) from Shanghai, China." (PMID 23883448, 2013).
type 2 diabetes (continued). "This same locus also trended toward statistical significance with variation in urinary albumin excretion in family members with type 2 diabetes (P = 0.032 [adjusted P = 0.192]) and in analyses expanded to include all relatives (P = 0.019 [adjusted P = 0.114])." (PMID 23555951, 2013). "Data from the Prevention of Renal and Vascular End Stage Disease (PREVEND) study showed that urinary albumin exertion independently predicted type 2 diabetes during a mean follow-up period of 4.2 years." (PMID 23805186, 2013). "Metformin significantly decreases the urine albumin excretion rate in patients with type 2 diabetes." (PMID 23781268, 2013). "The results showed that serum apelin was significantly higher in the patients with type 2 diabetes compared to healthy people (p<0.05) and that urinary albumin was positively correlated with serum apelin (R = 0.78, p<0.05)." (PMID 23577111, 2013). "It has been confirmed that both the amount of urinary albumin and eGFR value are useful to predict the outcome of kidney function in subjects with type 2 diabetes." (PMID 23316229, 2012). "Such increased retention of FL-modified albumin has been observed in a study that administerd angiotensin receptor blockade to patients with type 2 diabetes and microalbuminuria." (PMID 22558190, 2012). "Patients with type 2 diabetes and urinary albumin excretion in the high-normal and microalbuminuric range (15–300 mg/24h) were randomized to receive benfotiamine (n = 39) or placebo (n = 43)." (PMID 22792314, 2012). "A study in type 2 diabetic patients, CKD stage 2 and microalbuminuria reported that add-on eplerenone to enalapril caused a marked reduction in urine-albumin-creatinine-ratio (UACR) of 41–48%." (PMID 22073219, 2011). "Mortality in the coma sub-group receiving Gelofusine (6/23; 26%) was substantially greater than in those receiving albumin (1/25; 4%)." (PMID 16998584, 2006). "Multivariate regression analysis revealed that older age, male gender, serum concentrations of glycated albumin, hs-CRP, Lp (a), and creatinine were independent risk factors for CAD development in patients with type 2 diabetes." (PMID 17178005, 2006). "MR used blood cis-eQTL instruments for MLXIPL to estimate causal effects on type 2 diabetes (T2D) and urinary albumin-to-creatinine ratio (UACR), including a non-diabetic UACR stratum." (PMID 42064763, 2026). "A study shows that urinary retinol is a specific sign of tubular damage in people with type 2 diabetes and that urinary retinol is a better indicator of proximal tubule dysfunction in people with type 2 diabetes compared to urinary retinol-binding protein or albumin." (PMID 40607026, 2025). "This study was conducted to examine the glycemic markers (fasting blood glucose, glycated hemoglobin, fructosamine, and glycated albumin) in a sample of older adult patients with Type 2 diabetes and to determine the effect of auricular acupressure on both stress and quality of sleep." (PMID 40586734, 2025). "In addition to this, plasma albumin levels have been shown to inversely correlate with weight, and has been suggested as an indicator for the development of type 2 diabetes." (PMID 40806286, 2025). "The double-blind, double-dummy trial randomized 818 adults with CKD and type 2 diabetes [urine albumin–creatinine ratio (UACR) ≥100 to <5000 mg/g] to receive once-daily finerenone plus empagliflozin, finerenone alone or empagliflozin alone, all in addition to a renin–angiotensin system inhibitor." (PMID 40886054, 2025). "Most of these studies of DKD have been conducted based on clinical diagnosis: patients with type I or type II diabetes, persistent proteinuria: albumin creatinine ratio (ACR)≥30 mg/g, eGFR<60 ml/min, kidney transplantation, haemodialysis, or peritoneal dialysis." (PMID 39926344, 2025).